HDAC3 (histone deacetylase 3)
Diseases named in the same sentence as HDAC3 in open-access papers (continued):
Sharing a sentence is not in itself a finding about the gene and the disease.
glioma (24 papers, 2013 to 2025). A benign or malignant brain and spinal cord tumor that arises from glial cells (astrocytes, oligodendrocytes, ependymal cells). "HDAC3 expression is associated with the presence of VM in glioma tissues and contributes to VM in gliomas, possibly through the PI3K/ERK and MMPs/LAMC2 pathways." (PMID 36294763, 2022). "N25 induces autophagy in glioma cells through a new mechanism of upregulating Tip60 by inhibiting HDAC3, causing upregulation of ULK1 (Atg1) and Beclin-1 (Atg6), and resulting in induction of glioma cell autophagy." (PMID 29088860, 2017). "A recent study implicated that HDAC3 in the pathogenesis of pediatric glioma due to its promotion of glioma cell proliferation and migration, additionally, the level of HDAC3 expression was associated with tumor grades." (PMID 29088860, 2017). "Similarly, HDAC3 is overexpressed in aggressive glioma cell lines and is associated with poor prognosis and OS of GBM patients." (PMID 37370767, 2023). "The expression of HDAC3 is associated with the grade and prognosis of glioma patients." (PMID 34739189, 2022). "Furthermore, high HDAC3 expression was linked to poor prognosis in pediatric gliomas." (PMID 24244722, 2013). "We would like to offer a unique strategy for CNS infection and glioma therapy based on our study of the association between ZNF22, HDAC3, TJ-associated proteins, and BBB/BTB permeability." (PMID 36518188, 2022). "Patient age, CD4+ T cell density, and HDAC3 and HDAC4 mRNA expression were associated with high-grade glioma prognosis." (PMID 35359455, 2022). "Nonetheless, the precise link between HDAC3 expression and glioma patient prognosis remains contested." (PMID 36518188, 2022). "After the expression of HDAC3 is reduced by inhibitors, the growth and invasive abilities of human glioma cells are significantly weakened, which provides a new target for cancer treatment." (PMID 35545840, 2022). "In support of our findings, inhibition of HDAC3 by RGFP966 was shown to promote the differentiation of glioma initiating cells by impairing the TGF-ß signaling pathway mediated by SMAD7." (PMID 35365623, 2022). "The expression of ZNF22 and HDAC3 in glioma-exposed endothelial cells (GECs) of BTB were detected transcription real-time PCR or western blot." (PMID 36518188, 2022). "We revealed ZNF22 (P < 0.05) and HDAC3 (P < 0.05) to be highly expressed in gliomas in a difference analysis." (PMID 36518188, 2022). "In the present experiment, we found that HDAC3 played a positive role in the treatment of gliomas by increasing the permeability of the BBB/BTB." (PMID 36518188, 2022). "And according to survival curves, elevated HDAC3 expression was found to be detrimental to 5-year survival in gliomas (P < 0.05)." (PMID 36518188, 2022). "Meanwhile, after treatment with RGFP966 in glioma U87-MG cells, we found that autophagy induced by specific inhibition of HDAC3." (PMID 29088860, 2017). "Compared with normal brain tissues, glioma samples contained elevated expressions of the histone deacetylate HDAC3 but decreased levels of the histone acetyltransferase Tip60." (PMID 29088860, 2017). "In order to explore the influence of N25 on HDAC3 and Tip60 expression in glioma cells, U87-MG and U251 cells were treated with N25." (PMID 29088860, 2017). "In this study, the results suggest that overexpression of HDAC3 in glioma cells is closely related to the level of autophagy." (PMID 29088860, 2017). "Western blot results revealed that the expression of HDAC3 was significantly higher in glioma samples than normal brain tissue, however, the expression of LC3 and Tip60 were lower compared with normal brain tissue." (PMID 29088860, 2017). "In this study, we found that Coptis Chinensis functioned similarly to VPA to down-regulate STAT3 phosphorylation level by reducing the expression of HDAC3, then affected the function and biological characteristics of glioma cells." (PMID 29212474, 2017).
glioma (continued). "As long as we changed the expression of HDAC3 in tumor cells and increase autophagy in glioma cells, it can lead to autophagic death of glioma cells." (PMID 29088860, 2017). "Of all the genes studied, HDAC1 and HDAC3 were inverselyand significantly correlated with the survival of patients with gliomas, whenanalyzed collectively (p = 0.002 and p = 0.016 respectively)." (PMID 25791281, 2015). "Prior research centered on the relationship between HDAC3 and glioma development." (PMID 36518188, 2022). "Univariate Cox regression indicated that high expression levels of HDAC1, HDAC3, HDAC7 and HDAC9 were associated with poor OS of glioma, and elevated expression levels of HDAC4, HDAC5, HDAC6 and HDAC11 were associated with a favorable prognosis of glioma." (PMID 35545840, 2022). "It is also reported that inhibition of HDAC3 could induce cell autophagy in human glioma cells, and apoptosis in cholangiocarcinoma." (PMID 29498635, 2018). "Therefore, it is possible that overexpression of HDAC3 in glioma cells influences autophagy decrease and lead to glioma formation." (PMID 29088860, 2017). "In order to identify whether HDAC3 is over-expressed in adult gliomas, we collected 20 patient samples and measured HDAC3 protein expression by western blot." (PMID 29088860, 2017). "In conclusion, we could infer that Coptis Chinensis down-regulated the phosphorylated STAT3 level by reducing the expression of HDAC3 protein, which then affected the function of glioma cells and their biological characteristics." (PMID 29212474, 2017). "It was first proposed that HDACi induces glioma autophagy by inhibiting HDAC3." (PMID 29088860, 2017). "We first performed the univariate cox regression and found that the elevated expressions of HDAC7, HDAC3, and HDAC1 were associated with poor prognosis while increased expressions of HDAC6, HDAC5, HDAC4, and HDAC11 were favorable for prognosis in low-grade glioma." (PMID 36227941, 2022). "Therefore, we proposed a hypothesis that N25 induces autophagy probably through a new mechanism of upregulating Tip60 by inhibiting HDAC3, causing upregulation of ULK1 (Atg1) and Beclin-1 (Atg6), and resulting in induction of glioma cell autophagy." (PMID 29088860, 2017). "Moreover, we detected whether N25 induces autophagy in glioma cells by transmission electron microscope and analyzed the protein expression level of HDAC3, Tip60, LC3 in glioma samples by western blot." (PMID 29088860, 2017). "The overall survival time of glioma patients with low HADC1, HDAC3 and AKT1 expression is better (p < 0.05)." (PMID 40297576, 2025). "In glioma cells, strong nuclear expression of HDAC1, HDAC2, and NCOR2 has been observed, while NCOR1 and HDAC3 show weaker expression." (PMID 40940748, 2025). "The mRNA expression of HDAC1, HDAC2, HDAC3, HDAC6 and PI3K/AKT1 was analyzed in GBM and low grade glioma tissues." (PMID 40297576, 2025). "Ten glioma samples (5 IDH1 wildtype and 5 IDH1 mutant) were stained for various HDAC genes using internally validated antibodies (HDAC1, HDAC2, HDAC3, HDAC4, HDAC5, HDAC6 and HDAC7) and scored by a blinded neuropathologist (AK)." (PMID 37528157, 2023). "Then, using six HDAC genes (HDAC1, HDAC3, HDAC4, HDAC5, HDAC7, and HDAC9), we established a prognostic model for glioma patients, and this prognostic model was validated in an independent cohort population." (PMID 35545840, 2022). "GO analysis of ZNF22 and HDAC family in glioma using bioinformatics revealed that ZNF22 and HDAC3 were involved in regulating transcription GO: 0006357 (P < 0.05)." (PMID 36518188, 2022). "A model based on six HDAC genes (HDAC1, HDAC3, HDAC4, HDAC5, HDAC7, and HDAC9) can predict the overall survival of glioma patients well and these genes are potential therapeutic targets." (PMID 35545840, 2022). "Then, using six HDAC genes (HDAC1, HDAC3, HDAC4, HDAC5, HDAC7, and HDAC9), we established a prognostic model for glioma patients, and this prognostic model was validated in an independent cohort." (PMID 35545840, 2022).
glioma (continued). "The glioma cells show on average 90% higher HDAC1, 108% higher HDAC2 and 23% higher HDAC3 protein expression than astrocytes." (PMID 35365623, 2022). "The DFS-oriented study using GEPIA data showed that more transcripts of HDAC1 (HR:3.0, p < 0.0001), HDAC3 (HR:2.7, p = 2.1e−15), HDAC7 (HR:2.1, p = 3e−09), and HDAC9 (HR:1.5, p = 0.0026) accompanied with less DFS probabilities in glioma patients." (PMID 34540896, 2021). "Specifically, the mRNA level of HDAC1 (p = 1.25e−13), HDAC3 (p = 2.51e−09), HDAC7 (p = 1.43e−19), and HDAC8 (p = 3.48e−10) showed an increasing trend with glioma grade progressing." (PMID 34540896, 2021). "Nevertheless, N25 inhibited HDAC3 and up-regulated the protein expression of Tip60, ULK1, and Beclin-1 in glioma cells." (PMID 29088860, 2017). "Nevertheless, N25 inhibited HDAC3 and up-regulated the protein expression of Tip60, ULK1 (Atg1), and Beclin-1 (Atg6) after treatment of glioma cells with N25." (PMID 29088860, 2017). "We found that N25 induced autophagy, and HDAC3 was significantly elevated and Tip60 and LC3 significantly decreased in glioma samples compared with normal brain tissues." (PMID 29088860, 2017). "We additionally analyzed the protein expression level of HDAC3, Tip60, ULK1 (Atg1), and Beclin-1 (Atg6) after treatment with N25 in glioma cells." (PMID 29088860, 2017). "Moreover, analysis of a glioblastoma multiforme (GBM) clinical database indicated that lower expressions of HDAC1, HDAC3, and AKT1 correlated with better overall survival in glioma patients." (PMID 40297576, 2025). "Additionally, the strong nuclear expression of HDAC1, HDAC2, and NCOR2 in glioma cells, along with weak expression of NCOR1 and HDAC3, suggests a potential role for these proteins in tumor progression and as markers for patient prognosis." (PMID 40940748, 2025). "The OS analysis based on GEPIA revealed that the glioma patients with high expression levels of HDAC1 (HR:3.9, p < 0.0001), HDAC2 (HR:1.3, p = 0.024), HDAC3 (HR:4.4, p < 0.0001), and HDAC7 (HR:3.3, p < 0.0001) would face with more risks compared to the ones with low expression of these genes." (PMID 34540896, 2021). "Furthermore, HDAC3 was found to be significantly elevated and LC3 and Tip60 significantly decreased in glioma samples compared with normal brain tissues." (PMID 29088860, 2017). "Among all patients studied,the expression of HDAC1 and HDAC3 was inversely correlated withsurvival, whereas the expression of HDAC4, HDAC5, HDAC6,HDAC11 and SIRT1 was significantly and positively correlated withsurvival time of patients with gliomas." (PMID 25791281, 2015). "Moreover, in human U87MG GBM cells and rat C6 glioma cells, CM combination consisting of 8-CPT-cAMP (C) and MS-275 (M) targeting histone deacetylases 1 and 3 (HDAC1 and HDAC3) induced marked morphologic phenotype characterized by shrinking cell bodies and long synapse-like structure." (PMID 36805688, 2023). "Finally, we determined the HDAC3 protein, STAT3 phosphorylation and the core apoptosis protein Caspase 3 level in glioma cells treated with Coptis Chinensis using western blot to explore the effect of Coptis Chinensis intervention on the biological mechanisms in glioma cells." (PMID 29212474, 2017). "The expression levels of HDAC1, HDAC3, HDAC7, and HDAC9 were significantly elevated in the glioma patients compared with the nontumor group." (PMID 35545840, 2022). "qPCR was adopted to detect the expression of HDAC1, HDAC3, HDAC4, HDAC5, HDAC7 and HDCA9 in nontumor and glioma tissues." (PMID 35545840, 2022). "The expression of HDAC3, Tip60 and LC3 were measured in 20 glioma samples and 3 normal brain tissues." (PMID 29088860, 2017). "The results showed that 2.0 mM VPA or 5 mg/ml Coptis Chinensis could reduce the expression of P-STAT3, and Coptis Chinensis down-regulated HDAC3 and P-STAT3 in glioma cells, but it did not reduce the expression of STAT3." (PMID 29212474, 2017).
Insulin resistance (24 papers, 2016 to 2025). Increased resistance towards insulin, that is, diminished effectiveness of insulin in reducing blood glucose levels. "Their deficiency exacerbates hepatic inflammation and insulin resistance through impaired anti-inflammatory responses and attenuated HDAC3 activity." (PMID 40873449, 2025). "As expected, HDAC3 knockdown prevents free fatty acid-induced insulin resistance in myotubes, and diet-induced inflammation." (PMID 37006625, 2023). "Skeletal muscle-specific deletion of HDAC3 induces insulin resistance and impaired glucose uptake following exercise, and enhances fatty acid oxidation." (PMID 37006625, 2023). "Mice with skeletal muscle-specific knockout of Hdac3 (HDAC3-SkMKO mice) have been shown to have severe systemic insulin resistance." (PMID 35320455, 2022). "Low-grade chronic inflammation and insulin resistance induce histone deacetylase 3 (HDAC3) activity and expression in peripheral blood mononuclear cells." (PMID 35562979, 2022). "MS-275 pretreatment or HDAC3 knockdown dramatically alleviated lipotoxicity and protected against palmitic acid-induced insulin resistance and inflammation." (PMID 34301918, 2021). "High expression of the deacetylase HDAC3 correlated with high levels of proinflammatory markers and insulin resistance in peripheral blood mononuclear cells from T2D patients and hepatocytes from fat-fed E3 rats, which develop metabolic syndrome." (PMID 34638914, 2021). "On the other hand, HDAC3 inhibition has been shown to reciprocate insulin resistance in adipocytes by activation of PPARγ through its acetylation." (PMID 34071497, 2021). "Changes of histone deacetylase 3 (HDAC3) in peripheral blood mononuclear cells is reported to be strongly related to insulin resistance and related proinflammatory mediators in patients with type 2 diabetes." (PMID 31849831, 2019). "Majority of the altered lncRNAs were positively correlated with poor glycemic control, insulin resistance, transcriptional markers of senescence, inflammation, and HDAC3 and negatively correlated with telomere length." (PMID 30139387, 2018). "In contrast, expression levels of lncRNAs, viz., SALRNA1 and THRIL, were negatively correlated to glycemic control, insulin resistance, markers of senescence, inflammation, and HDAC3 and positively correlated to telomere length." (PMID 30139387, 2018). "Secondly, increased HDAC3 activity/HDAC3 mRNA level was positively correlated to all the inflammatory markers profiled, poor glycemic control, and insulin resistance." (PMID 27904654, 2016). "Moreover, Hdac3 knockdown or Mbnl1 overexpression significantly improved HFD-induced insulin resistance and glucose intolerance." (PMID 39580381, 2024). "Increased HDAC3 or NCoR1 activity could limit lipolysis, resulting in a reduction in the breakdown of stored triglycerides and perhaps contributing to insulin resistance." (PMID 37674539, 2023). "In another report, inhibition of HDAC3 by butyrate was shown to prevent the development of insulin resistance and obesity in high fat-fed mice via triggering PGC1α/AMPK activation and increasing adaptive thermogenesis and fatty acid oxidation in skeletal muscle and brown fat." (PMID 34071497, 2021). "Inhibition of HDAC3 in adipocytes increased PPARγ acetylation and the expression of PPARγ target genes, including adipokines and adipocyte protein 2, resulting in decreased insulin resistance." (PMID 34638914, 2021). "Activation of HDAC3 epigenetic signature can contribute to developing insulin resistance in T2DM." (PMID 34071497, 2021). "Thus, HDAC3 can affect insulin secretion, glucose tolerance, lipotoxicity, insulin resistance, and inflammation in pancreatic cells via multiple mechanisms." (PMID 34301918, 2021). "For instance, hepatic overexpression of DGAT2, or liver-specific deletion of Histone deacetylase 3 (Hdac3), causes severe TG accumulation in liver, but does not promote insulin resistance in mice." (PMID 32170127, 2020).
Insulin resistance (continued). "However, the effects of HDAC3 inhibition on free fatty acid-induced insulin resistance and inflammation in the C2C12 myotubes and skeletal muscle of high fat (HF)/high fructose (HFr) diet mice is not known." (PMID 33362555, 2020). "In addition, patients with type 2 diabetes showed higher HDAC3 expression in peripheral blood mononuclear cells, along with simultaneous activation of pro-inflammatory markers and insulin resistance." (PMID 33362555, 2020). "Indeed, myeloid cell-specific Irs2-deficient mice show impairment of IL-4-induced M2a-subtype macrophage activation, as a result of stabilization of the FoxO1/HDAC3/NCoR1 corepressor complex, resulting in insulin resistance under the HF diet condition." (PMID 30451856, 2018). "Interestingly, HDAC3 activity/HDAC3 mRNA levels positively correlated to proinflammation, poor glycemic control, and insulin resistance." (PMID 27904654, 2016). "Interestingly, increased HDAC3 activity and mRNA expression were observed in the PBMCs of type 2 diabetic patients in comparison with control subjects and HDAC3 activity positively correlated with proinflammatory markers, fasting plasma glucose, and insulin resistance." (PMID 39050859, 2024). "Recent experimental results showed that histone deacetylase 3 (HDAC3) expression and activity were significantly increased in the hippocampus and cortex of db/db mice, and its activity/mRNA levels positively correlated with proinflammation, poor glycemic control, and insulin resistance." (PMID 37213537, 2023). "Interestingly, this association was lost when adjusted for insulin resistance, implying that the association between HDAC3 and T2DM could be closely linked to insulin resistance state." (PMID 27904654, 2016). "HDAC3-SMKO mice showed glucose intolerance and muscle insulin resistance, but surprisingly, these mice showed enhanced exercise capacity and muscle fatigue resistance compared to wild-type (WT) littermate controls." (PMID 37674539, 2023). "Increased HDAC3 activity or levels in patients with T2DM is correlated with inflammatory marker expression, poor glycemic control, and insulin resistance." (PMID 33736642, 2021). "Experimental mice lacking HDAC3 have increased glucose tolerance, decreased insulin resistance and lower fat accumulation." (PMID 37445790, 2023). "Indeed, increased HDAC3 activity in PBMCs from T2DM patients has been directly correlated with inflammation and insulin resistance, and negatively with SIRT-1 level." (PMID 29330620, 2018). "The data presented here suggest that treatment with MS-275 may help restore lipotoxicity-induced insulin resistance and inflammation in skeletal muscle via the inhibition of HDAC3, rather than HDAC1/2." (PMID 33362555, 2020). "Indeed, when NCoR1 or HDAC3 is specifically deleted in hepatocytes a lipogenic program is activated leading to steatosis without evidence of insulin resistance or glucose intolerance." (PMID 31404087, 2019).